UHMK1 (U2AF homology motif kinase 1)
Description:
Upon serum stimulation, phosphorylates CDKN1B/p27Kip1, thus controlling CDKN1B subcellular location and cell cycle progression in G1 phase. May be involved in trafficking and/or processing of RNA (By similarity).
Synonyms: P-CIP2; KIS; KIST
Tractability: Small molecule: it belongs to a druggable protein family. PROTAC: it is named in the literature on targeted protein degradation; ubiquitination databases record sites on it.
Gene: Protein-coding gene on chromosome 1 (162,497,251 to 162,529,631, forward strand). Ensembl gene ENSG00000152332.
Subcellular location: Nucleus
Subcellular location (Human Protein Atlas): Nucleoplasm
Pathways (Reactome):
Signal Transduction: Estrogen-dependent nuclear events downstream of ESR-membrane signaling
Gene Ontology:
Molecular function: ATP binding; protein binding; protein serine/threonine kinase activity; ribonucleoprotein complex binding; nucleic acid binding; protein kinase activity; protein serine kinase activity; RNA binding
Biological process: regulation of cell cycle; regulation of protein export from nucleus; neuron projection development; peptidyl-serine phosphorylation; positive regulation of translational initiation
Cellular component: nucleoplasm; nucleus; axon; dendrite cytoplasm; neuronal ribonucleoprotein granule
Genetic constraint (gnomAD): Loss-of-function variants: 17 observed, 41.07 expected, observed/expected ratio (o/e) 0.41, 90% interval 0.28 to 0.62. The upper end of that interval is the gene's LOEUF score, 0.62, which puts it in group 2 of 6, group 1 being the genes least tolerant of losing a copy. Missense variants: 440 observed, 510.48 expected, observed/expected ratio (o/e) 0.86, 90% interval 0.8 to 0.93. Synonymous variants: 222 observed, 197.59 expected, observed/expected ratio (o/e) 1.12, 90% interval 1.01 to 1.26.
Homologues: Orthologues: chimpanzee UHMK1 (99% identical), macaque UHMK1 (99% identical), pig UHMK1 (99% identical), rabbit UHMK1 (99% identical), mouse Uhmk1 (99% identical), rat Uhmk1l1 (99% identical), dog UHMK1 (99% identical), guinea pig UHMK1 (98% identical), zebrafish uhmk1 (71% identical), Caenorhabditis elegans cpf-2 (7% identical), Drosophila melanogaster CstF64 (7% identical), Caenorhabditis elegans R06C1.4 (2% identical). Paralogues in human: U2AF2 (23% identical), CSTF2 (10% identical), CSTF2T (10% identical), RBMX2 (6% identical), ZCRB1 (6% identical).
Diseases named in the same sentence as UHMK1 in open-access papers:
UHMK1 is named in the same sentence as 41 diseases in open-access papers, as found by Europe PMC text mining. Sharing a sentence is not in itself a finding about the gene and the disease. The quoted sentences say what the papers report.
gastric cancer (11 papers, 2021 to 2025). A primary or metastatic malignant neoplasm involving the stomach. "In recent years, UHMK1 dysregulating process or mutating process was suggested as one high-penetrant element inside various tumors of humans (e.g., gastric cancer as well as CRC)." (PMID 34109193, 2021). "Recently, a function of UHMK1 in the progression of hepatocellular carcinoma, gastric cancer, and ovarian cancer has been reported, but the function of UHMK1 in PDAC is unclear." (PMID 35359403, 2022). "Emerging evidence has indicated UHMK1 to be an essential factor in many kinds of tumors, including liver cancer, ovarian cancer, and gastric cancer." (PMID 35501324, 2022). "U2AF homology motif kinase 1 enhances the de novo purine synthesis pathway, thereby promoting gastric cancer development." (PMID 35092699, 2022). "In addition, UHMK1 upregulation significantly promotes gastric cancer growth and metastasis possibly via metabolic networks." (PMID 37744384, 2023). "Blocking U2AF homology motif kinase 1 (UHMK1) could inhibit gastric cancer progression by downregulating the expression of purine metabolism-associated target genes." (PMID 35477416, 2022). "Interestingly, UHMK1 promotes the progression of gastric cancer through reprogramming of nucleotide metabolism." (PMID 35359403, 2022). "U2AF homology motif kinase (UHMK1) has been discussed in colorectal cancer, HCC, gastric cancer, and pancreatic ductal adenocarcinoma." (PMID 38287425, 2024). "UHMK1 also contributes to purine metabolism reprogramming by regulating the NCOA3/ATF4 axis and significantly promotes gastric cancer development." (PMID 35501324, 2022). "Our results are consistent with previous work, demonstrating enhanced UHMK1 expression in clinical PDAC specimens, PDAC cell lines, gastric cancer, liver cancer cells, and leukemia cells." (PMID 35359403, 2022).
colorectal cancer (7 papers, 2021 to 2025). A primary or metastatic malignant neoplasm that affects the colon or rectum. "In colorectal cancer, hyperactivating UHMK1/STAT3 positive feedback loop contributes to colorectal cancer cell proliferation and chemoresistance." (PMID 40918462, 2025). "For example, miR-323a-3p inhibits ErbB4 and affects depression, inhibits UHMK1 to down-regulate tumor growth in colorectal cancer, and inhibits PUM1/eIF2 axis in breast cancer." (PMID 35319011, 2022). "However, it remains to be elucidated whether UHMK1 plays a role in the development of colorectal cancer (CRC)." (PMID 35501324, 2022).
hepatocellular carcinoma (6 papers, 2020 to 2024). A malignant tumor that arises from hepatocytes. "Bioenergetic alteration-dependent activation of AMPK was found to occur in hepatoma cells via COX5B regulation of UHMK1 expression." (PMID 36551283, 2022). "As UHMK1 is a kinase, it is possible that UHMK1 impacted hepatoma cells proliferation and migration via modulating hepatoma growth-related protein(s) or pathway(s)." (PMID 32580279, 2020). "The COX5B-mediated regulatory event on UHMK1 expression was subsequently demonstrated as bioenergetic alteration-dependent activation of AMPK in hepatoma cells." (PMID 32580279, 2020). "Next, to determine whether the relationship between COX5B and UHMK1 could also be observed in samples from patients with hepatoma, the western blot and qRT-PCR were conducted." (PMID 32580279, 2020). "Similarly, the migratory ability was also rescued by elevating UHMK1 expression in hepatoma cells under COX5B depletion." (PMID 32580279, 2020). "Recently, a report demonstrated that UHMK1 expression was drived by an oncogene called yes-associated protein 1 (YAP1), a key factor in Hippo signaling pathway, through a combination effect of FOXM1 in hepatoma." (PMID 32580279, 2020). "Additionally, YAP-dependent induction of UHMK1 has been reported to support the nuclear enrichment of the MYBL2 oncogene, leading to the proliferation of hepatocellular carcinoma cells as demonstrated in YAP-deficient mice and human hepatocellular carcinoma tissues." (PMID 35359403, 2022). "Lowering UHMK1 expression restrained activation of ERK, which together with the ULK1-induced autophagy, inhibited cell proliferation and migration in hepatoma cells." (PMID 32580279, 2020). "The mRNA and protein levels of UHMK1 and ULK1 were then examined for validation by using samples from COX5B downregulated or overexpressed hepatoma cells." (PMID 32580279, 2020). "Moderate outcomes were observed in those with either higher COX5B but lower UHMK1 or lower COX5B but higher UHMK1 expression, suggesting the COX5B-UHMK1 axis might be crucial for hepatoma progression." (PMID 32580279, 2020). "Next, to examine whether UHMK1 indeed served as a downstream effector of COX5B in modulating hepatoma progression, the rescue experiment was conducted by overexpressing UHMK1 in cells with or without siRNA knockdown of COX5B." (PMID 32580279, 2020).
breast carcinoma (5 papers, 2011 to 2025). "Furthermore, we detected a significant upregulation of UHMK1 expression in advanced breast cancer, cervical squamous cell carcinoma and endocervical adenocarcinoma, lymphoid neoplasm, diffuse large B-cell lymphoma, esophageal carcinoma, skin cutaneous melanoma, stomach adenocarcinoma, and thymoma." (PMID 35359403, 2022).
schizophrenia (5 papers, 2007 to 2025). A major psychotic disorder characterized by abnormalities in the perception or expression of reality. "Genetic variants in UHMK1 have been associated with schizophrenia, and gene expression evaluations have been performed in mouse brain with particular interest in pharmacological treatment effects." (PMID 28417008, 2017). "Similarly, gene DNTT and UHMk1 are predicted as biomarkers in Schizophrenia." (PMID 38674383, 2024).
ovarian carcinoma (4 papers, 2020 to 2024). A malignant neoplasm originating from the surface ovarian epithelium. "For example, serine 10 phosphorylation by UHMK1, U2AF homology motif kinase 1, promotes p27 translocation from the nucleus to the cytoplasm depending on nuclear export protein CRM1, chromosomal maintenance 1, resulting in p27 inactivation and ovarian cancer cell proliferation." (PMID 33050036, 2020).
pancreatic cancer (4 papers, 2021 to 2024). "Interestingly, we observed that there are reports of mutations and copy number variation in PAIP2B, PRDX1, RNASE1, BARD1, UHMK1, and RPL3L genes associated with pancreatic cancer." (PMID 34912796, 2021). "To examine UHMK1 expression in different cancer stages, we performed immunohistochemistry using a commercially available pancreatic cancer tissue array with 91 malignant tissues and 5 nonmalignant pancreatic tissues along with patient information on clinical stage and pathology grade." (PMID 35359403, 2022).
colon cancer (3 papers, 2017 to 2022). "From public database queries for UHMK1 genetic and epigenetic modifications in colon cancers, we found that gene amplification, nucleotide substitution, and other genomic changes in UHMK1 were associated with poor overall survival in patients." (PMID 35151311, 2022). "Consistent with those online database analyses regarding mRNA, the protein expression of UHMK1 was also significantly increased in colon cancer tissues." (PMID 35501324, 2022). "Our findings expand our understanding about functional natural substrates of UHMK1 and further demonstrated the importance of coilin phosphorylation in colon cancers, especially in context of drug sensitivity and resistance." (PMID 35151311, 2022). "Subsequently, immunohistochemical analysis (IHC) was conducted to examine UHMK1 protein expression in a colon tissue microarray, which consists of 86 paired colon cancer and paracancerous tissues and eight cases of individual colon cancer specimens." (PMID 35501324, 2022). "In conclusion, we identified that coilin is phosphorylated at serine residues by UHMK1 in colon cancer cells, and this phosphorylation subsequently regulates CB assembly and contributes to colon cancer cell resistance to 5-FU." (PMID 35151311, 2022). "Altogether, these results clearly demonstrate that NRF3 promotes colon cancer cell proliferation by activating UHMK1 gene expression." (PMID 28970512, 2017). "We next aimed to address whether UHMK1 could be functionally involved in the regulation of 5-FU sensitivity in colon cancer cells." (PMID 35151311, 2022). "In addition, upregulation of UHMK1 to about doubled levels was found in 5-FU-resistant human colon cancer cells in HCT-116 background following increasing dosing of 5-FU for more than 6 months (GSE56322), suggesting the important roles of UHMK1 in the development of chemoresistance." (PMID 35151311, 2022).
leukemia (3 papers, 2014 to 2024). A malignant (clonal) hematologic disorder, involving hematopoietic stem cells and characterized by the presence of primitive or atypical myeloid or lymphoid cells in the bone marrow and the blood. "However, there are also contradictory data indicating that UHMK1 silencing does not affect cell cycle progression in U937 leukemia cells." (PMID 35359403, 2022).
melanoma (3 papers, 2022 to 2024). A malignant, usually aggressive tumor composed of atypical, neoplastic melanocytes. "It has been reported in melanoma patients that UHMK1 regulates metabolic reprogramming during targeted therapy through selective mRNA processing and translation, resulting in resistance to targeted therapy." (PMID 38364250, 2024). "The siUHMK1 + Tram combination resulted in more robust growth inhibition in multiple NRAS mutant melanoma cell lines providing evidence that UHMK1 depletion can also play a role in MAPK targeted therapy response in the setting of a different oncogenic driver." (PMID 35232962, 2022). "Because the UHM RNA processing domain is essential for UHMK1’s role in the BRAFi response, we suggest these translational mechanisms contribute to the metabolic plasticity observed in melanoma cells following BRAFi in order to facilitate the survival." (PMID 35232962, 2022). "Viewed together, these data confirm a role for the UHMK1 RNA processing pathway in MAPK pathway inhibitor responses in BRAFV600 melanoma cells both in vitro and in vivo, and demonstrate UHMK1 inactivation is sufficient to delay targeted therapy resistance." (PMID 35232962, 2022). "We next investigated whether UHMK1 can also promote adaptive reprogramming of mitochondrial metabolism in response to BRAFi in melanoma cells." (PMID 35232962, 2022). "Finally, we assessed the effectiveness of UHMK1 depletion in combination with the MEK inhibitor trametinib (tram) in the setting of NRAS mutant melanoma." (PMID 35232962, 2022). "Indeed, we observe a significant delay in resistance to MAPK targeted therapy in our preclinical mouse model implanted with multiple melanoma cell lines depleted of UHMK1." (PMID 35232962, 2022). "Notably, nuclear accumulation of poly(A)+ mRNA was also observed in UHMK1 depleted cells, confirming a role for UHMK1 in mRNA export in the context of melanoma cells." (PMID 35232962, 2022). "Together these data confirm a role for UHMK1 in glycolytic, proliferative, and viability responses to BRAFi in BRAFV600 melanoma cells." (PMID 35232962, 2022). "We next investigated the role of UHMK1 in the regulation of proliferative and metabolic responses to BRAFi in a panel of BRAF mutant melanoma cell lines." (PMID 35232962, 2022). "We propose selective mRNA processing and translation by UHMK1 constitutes a mechanism of non-genetic resistance to targeted therapy in melanoma by controlling metabolic plasticity induced by therapy." (PMID 35232962, 2022). "Because the available UHMK1 antibodies do not specifically detect the endogenous human protein in our melanoma cells, we also confirmed increased levels of its key target p27, which is degraded following phosphorylation by UHMK131." (PMID 35232962, 2022). "We were next interested in testing the hypothesis that UHMK1 depletion would improve response and delay resistance following treatment with the current standard of care for BRAFV600 melanoma patients, a BRAF + MEK inhibitor combination." (PMID 35232962, 2022). "Here, we define a mechanism of non-genetic drug adaptation in melanoma whereby adaptive mitochondrial metabolism is regulated at the level of mRNA export and translation, and we identify the RNA processing kinase UHMK1 as a central factor in this process." (PMID 35232962, 2022).
pancreatic ductal adenocarcinoma (3 papers, 2024 to 2025). An infiltrating adenocarcinoma that arises from the epithelial cells of the pancreas. "For example, elevated UHMK1 expression correlates with poor prognosis, while silencing UHMK1 inhibits tumor proliferation and xenograft growth in pancreatic ductal adenocarcinoma." (PMID 40918462, 2025).
Anxiety (2 papers, 2012 to 2016). Intense feelings of nervousness, tension, or panic often arise in response to interpersonal stresses. "In line with our findings, UHMK1 knockout mice display a distinct deficit in fear conditioning, which is accompanied by downregulation of genes implicated in the aetiology of anxiety and fear, including multiple components of GABAA receptors." (PMID 27043157, 2016).
bladder cancer (2 papers, 2015 to 2018). "We further evaluated the expression of DIAPH3, LMAN1, PPP2R5E, and UHMK1 in bladder cancer cell lines upon LINC00857 knockdown." (PMID 29856124, 2018). "Mechanistically, WDR5 regulated various functions in bladder cancer by mediating the transcription of cyclin B1, cyclin E1, cyclin E2, UHMK1, MCL1, BIRC3 and Nanog by histone H3 lysine 4 trimethylation." (PMID 25656485, 2015).
autoimmune disease (1 paper, 2023). A disorder resulting from loss of function or tissue destruction of an organ or multiple organs, arising from humoral or cellular immune responses of the individual to their own tissue constituents. "Altered DNA methylation of genes, such as, PON1, ADARB2, USP16, UHMK1, and DISC1, was previously reported to be related to cancer or autoimmune diseases." (PMID 37744384, 2023).
colon adenocarcinoma (1 paper, 2022). "Meanwhile, microarray dataset analyses from Hong’s dataset and Kaiser’s dataset indicated the upregulation of UHMK1 in colon adenocarcinoma tissues compared with normal controls." (PMID 35501324, 2022). "According to TCGA-COAD (The Cancer Genome Atlas Colon Adenocarcinoma) data collection, UHMK1 mRNA expression was significantly higher in tumor tissue (n = 275) than normal tissue (n = 349)." (PMID 35501324, 2022).
hepatic cirrhosis (1 paper, 2024). "Notably, the expression of FOXA1, GSTZ1, WDR72 and UHMK1 was more upregulated in the tissues of individuals with hepatic cirrhosis than those with liver failure, although statistical significance was not achieved." (PMID 38287425, 2024). "Furthermore, the liver tissues of patients with liver failure and hepatic cirrhosis exhibited downregulated expression of CBS, CYP1A2, FOXA1, GSTZ1, WDR72 and UHMK1 when compared to healthy controls." (PMID 38287425, 2024).
liver fibrosis (1 paper, 2024). "The mechanism of CBS, CYP1A2, FOXA1, GSTZ1, WDR72 and UHMK1 in the progression of liver fibrosis is still unclear." (PMID 38287425, 2024). "According to the validation of clinical specimens, CBS, CYP1A2, FOXA1, GSTZ1, WDR72 and UHMK1 were specifically expressed in patients with liver fibrosis or hepatocirrhosis." (PMID 38287425, 2024). "Our research revealed that the elevated expression level of UHMK1 in patients with HCV-induced early liver fibrosis predicted a great prognosis." (PMID 38287425, 2024). "Nevertheless, the role of UHMK1 in hypoxia and liver fibrosis needs to be discussed further." (PMID 38287425, 2024). "However, the role of UHMK1 in liver fibrosis remains to be explored." (PMID 38287425, 2024).
lymph node metastasis (1 paper, 2025). "Increased UHMK1 expression was observed in patients with high Gleason scores and lymph node metastasis." (PMID 40918462, 2025).
prostate carcinoma (1 paper, 2025). A carcinoma that arises from epithelial cells of the prostate gland. "In this study, our aim was to investigate the expression of UHMK1 in prostate cancer, as well as its biological functions and regulatory mechanisms during prostate progression." (PMID 40918462, 2025).
prostate tumor (1 paper, 2025). "To further evaluate the effect of UHMK1 on PCa tumorigenicity in vivo, we established an orthotopic human prostate tumor model by injecting stably silenced UHMK1 and control PC3 cells." (PMID 40918462, 2025).
serous ovarian cancer (1 paper, 2022). "UHMK1 has been detected as an autoantibody biomarker for serous ovarian cancer using an ELISA platform against a total of 153 serum samples (63 cases with 30 benign disease controls and 60 healthy controls)." (PMID 35359403, 2022).